MMP2 (matrix metallopeptidase 2)
Diseases named in the same sentence as MMP2 in open-access papers (continued):
Sharing a sentence is not in itself a finding about the gene and the disease.
breast cancer (continued). "A study of a breast cancer cell lines stimulated with EGF showed an increase in MMP9 but not MMP2, but this increase was not inhibited by the tyrosine kinase inhibitor PD153035." (PMID 15083203, 2004). "Here the patient group presenting an MMP-2-negative primary breast carcinoma without a lymph node involvement enjoyed an excellent prognosis for survival, 100% of the patients being alive after 10 years of follow-up." (PMID 14520459, 2003). "The patients with an MMP-2-negative breast carcinoma form a relatively large patient group when the incidence of breast carcinoma is taken into consideration." (PMID 14520459, 2003). "Furthermore, WISP1 appears to act as a regulator of extracellular matrix remodeling in breast cancer, broadly enhancing the expression of matrix metalloproteinases, including MMP1, MMP2, MMP9, and MT1-MMP, and shifting the MMP/TIMP balance toward a proteolytic phenotype." (PMID 41597235, 2026). "To ensure the reliability of our data, we used in vitro A549 lung adenocarcinoma and MDA-MB-231 breast cancer triple-negative cell cultures to demonstrate the herb extract’s effects on PI3K and Akt enzymes and clarify how PI3K/Akt/mTOR mediation regulates TNFα, VEGFα, COX-2, MMP-2, and Caspase-3." (PMID 40179064, 2025). "In breast cancer, platelets MPs can promote adhesion of mammary cancer cells to human umbilical vascular endothelial cells (HUVEC), through the transfer of CD41, and also induce chemotaxis, invasion and upregulate the production of matrix metalloproteases (MMP) such as MMP-2 and MMP-9." (PMID 39510381, 2024). "Tang and co-workers reported that, in breast cancer cells, quercetin significantly inhibited the protein expression of MMP-2 and MMP-9 and increased the TIMP-1 and TIMP-2 levels in a concentration-dependent manner; it also suppressed the activity of MMP-2 and MMP-9 based on gelatin zymography." (PMID 39335164, 2024). "Given that MMP2 and MMP9 play important roles in degrading type IV collagen with MMP9 being particularly influential in breast cancer metastasis, we sought to determine if GATA4 might also counteract breast cancer metastasis by modulating MMP9." (PMID 38653973, 2024). "Furthermore, the gene knockout mechanism of MMP-2, MMP-7, and MMP-9 shown by CRISPR-Sp cas9 to improve cancer treatment at the gene level will also pave the way for future approaches in the treatment of breast cancer." (PMID 38774755, 2024). "The combined treatment reduced the rate of BC cell migration by 62% and the expression of gelatinase enzymes MMP-9 and MMP-2 genes, which have a key role in the metastasis of breast cancer cells." (PMID 37175156, 2023). "In addition, several MMPs that contribute to the proteolysis of collagen-425,26, including MMP2, MMP3, MMP9, and MMP14, were upregulated in either lung fibroblasts exposed to breast cancer cell-conditioned media, or premetastatic lungs in metastatic primary tumor-bearing mice." (PMID 37903851, 2023). "Apart from this, chlorin e6 (Ce6), berberrubine (BBR) and matrix metalloproteinase-2 (MMP-2) response peptide (PLGVRKLVFF) were coupled by linkers to form a linear triblock molecule BBR-PLGVRKLVFF-Ce6 (BPC), which can self-assemble into nanoparticles for chemo-photodynamic therapy of breast cancer." (PMID 38017573, 2023). "Propoxur exposure increased MMP-2 expression and invasion of cancer cells through the activation of the mitogen activated protein kinase (MAPK) member extracellular related kinase (ERK)/nuclear factor erythroid 2–related factor 2 (Nrf2) signaling in breast cancer." (PMID 37511154, 2023). "Recently bLF was reported to inhibit the invasion of breast cancer cells via the inhibition of FAK phosphorylation at tyrosine (Tyr)-397, and enhanced AMP-activated protein kinase activity (AMPK) thereby inhibited the expression of MMP-2 (Gelatinase A) and MMP-9 (Gelatinase B)." (PMID 36839884, 2023).
breast cancer (continued). "In addition, plasma MMP-2 and MMP-9 were significantly reduced in breast cancer patients after surgery, so both MMP-2 and MMP-9 could be used as markers of breast cancer disease response to therapy." (PMID 37496657, 2023). "Currently available reports have tried to explain RBMS3′s anticancer activity in all types of breast cancer through the inhibition of the Wnt/β-catenin pathway and the inhibition of the epithelial–mesenchymal transition process (EMT), mainly by impacting on TWIST, PRRX1, or MMP2." (PMID 36769184, 2023). "Therefore, the close interaction between SCUBE3 and MMP-2/9 may suggest the role of SCUBE3 in the metastasis and progression of breast cancer, though future mechanistic studies are needed to verify this possibility." (PMID 34006286, 2021). "In contrast to constitutively expressed MMP-2, MMP-9 is inducible, and represents one of the most important proteinases that mediates tumor progression in human lung cancer, gliomas, pancreatic cancer, head and neck cancer, prostate cancer, gastric cancer, and breast cancer." (PMID 34769032, 2021). "The inhibitory effect of piperine on breast cancer cells’ migration relied not only on the direct inhibition of MMPs, but also on the downregulation of HER2 expression, which is a key regulator of the metastatic potential of breast cancer cells that promotes the expression of MMP-2/9." (PMID 33256185, 2020). "Furthermore, we found that silencing of KIF3B decreased the expression of Dvl2, phospho-GSK-3β, total and nucleus β-catenin, then subsequent down-regulation of Wnt/β-catenin signaling target genes such as CyclinD1, C-myc, MMP-2, MMP-7 and MMP-9 in breast cancer cells." (PMID 33542902, 2020). "In addition, the driving force of adipocytes in breast cancer metastasis can also be attributed to cytokine-mediated communication between these cells, which results in the upregulation of metastasis-related factors such as PLOD2 and MMP-2 in cancer cells." (PMID 33371368, 2020). "Similarly, the exogenous CXCL1 could partly restore MMP2 and MMP9 levels that were suppressed by XIAOPI formula, suggesting that XIAOPI might inhibit the invasion of breast cancer cells in a CXCL1 dependent manner." (PMID 32213179, 2020). "To assess whether DANCR regulates EMT or cancer stemness of malignant breast cancer cells, we first examined the expressions of EMT‐related biomarkers, including SNAIL1, SLUG, MMP‐2, MMP‐9, E‐cadherin, and Vimentin in shDANCR vs. shNC (MDA‐MB‐231 and MDA‐MB‐468) cells." (PMID 31860165, 2020). "This study evaluated the effect of matrix metalloproteinases-2 (MMP-2) gene silencing using MMP-2 shRNA expression plasmids (pMMP-2) on IR induced cytotoxicity and DNA damage by MTT, dead green, γH2AX and comet assays in human normal dermal fibroblasts (HDFs) and MCF-7 human breast cancer cells." (PMID 31367263, 2019). "A drop in MMP-2 and MMP-9 activity was detected in addition to its effects on other several apoptotic pathways after quercetin treatment in multiple cancer cell lines i.e., human head and neck squamous cell carcinoma (HNSCC), colon cancer (Caco-2 cells), and breast cancer (MCF-7 cells)." (PMID 31064104, 2019). "In addition, the literature has shown increased expression of MMP-2 and -9 in breast cancer in women with lymph node metastasis as compared to the expression of these gelatinases in breast cancer without metastases in axillary lymph nodes." (PMID 31839881, 2019). "Recent studies in breast cancer cells have revealed that CXCR7 activation by SDF‐1 increases components regulating cell adhesion and cell–matrix interaction, such as vascular adhesion molecule VCAM‐1 and matrix metalloproteinases MMP‐2 and MMP‐9, and SDF‐1 also promoted MMP‐9 expression in OC cells." (PMID 30051594, 2018).
breast cancer (continued). "In addition to collagen and fibronectin modulation, hypoxia can promote ECM degradation and remodeling by upregulating the expression of MMPs, with MMP-2 upregulation observed in pancreatic cancer, and MMP-9 expression observed in breast cancer in response to low oxygen." (PMID 30487436, 2018). "Interestingly, MMP2 and CHOP were also upregulated in human tumors with low IGF-1R, similar to our mouse model, whereas these two genes were unchanged in TNBC compared to ER+/PR+ breast cancer." (PMID 30458886, 2018). "Previous in vitro studies showed that ATRA inhibited MMP-2 expression in human cancer cell lines from glioblastoma, breast cancer, lung cancer, ovarian cancer, chondrosarcoma, and osteosarcoma, but it did not affect or enhance MMP-2 expression in neuroblastoma cell line." (PMID 30225259, 2018). "A recent study further supports a potential role of MMP2 in breast-to-brain metastasis, as it was found to belong to 5-gene expression signature (together with CXCL12, MMP11, VCAM1, MME) discriminating between primary breast cancer and breast cancer brain metastases." (PMID 29312881, 2017). "In contrast to the effects of BST‐2 on breast cancer cells, in HT1080 (human fibrosarcoma epithelial cell line) and MDCK (canine kidney cells) cells, overexpression of BST‐2 decreased cell growth and migration due to reduced matrix metalloproteinase 2 (MMP‐2) activity." (PMID 27042298, 2016). "Moreover, MMP2 seems to have no prognostic value for breast cancer patients while the prognostic impact of tissue expression or circulating level of MMP9 remains controversial." (PMID 26921265, 2016). "In addition, FN triggers MMP-2 and MMP-9 expression which are involved with cell invasion and migration through binding of RGD sequence of α5β1 integrin in several human carcinoma cells, including breast cancer cells." (PMID 26637807, 2016). "In addition, loquat leaf and seed extracts also showed significant anti-metastatic properties by inhibition of the migration and invasion of MDA-MB-231 human breast cancer cells and B16F10 melanoma cells, which was partially through the inhibition of matrix metalloproteinase-2 (MMP-2) and MMP-9." (PMID 27929430, 2016). "From our results we conclude that TNF-α-induced activation of the MAPK/ERK signaling pathway may promote breast cancer cell migration via both upregulation of MMP9, CD26 and FAP-α and concentration of these proteases, as also MT1-MMP and MMP2, in the lipid rafts." (PMID 27042827, 2016). "When MCF7S1 breast cancer cells were cultured with mammary fibroblasts in 3D culture, the fibroblasts increased expression of the S100A4 metastasis promoting protein, which subsequently increased MMP-2 activity and cytokine secretion within the coculture to promote breast cancer cell invasion." (PMID 25856378, 2015). "An increased expression of MMPs, particularly MMP-2 (gelatinase A; 72-kDa type IV collagenase) and MMP-9 (gelatinase B; 92-kDa type IV collagenase), has been correlated extensively with the malignancy of tumors and poor survival among patients, especially those with breast cancer." (PMID 23878598, 2013). "In breast cancer cells, miR-340 suppressed tumor cell migration and invasion by lowering the abundance of c-Met, a factor that promotes expression of MMP-2 and MMP-9; MMP-2 was additionally repressed by miR-29b in HCC cells, attenuating HCC cell invasiveness and angiogenic activity." (PMID 23325049, 2013). "Thus, our data suggest that MMP-2 and MMP-9 may play fundamental roles in breast cancer invasion and metastasis." (PMID 23935727, 2013). "To determine whether Bcl-w plays an invasion-promoting role in general, we examined whether the protein enhances p-GSK3β, β-catenin and MMP-2 expression in several types of cancer cells, including U373, U87MG (glioma), MDA-MB-231 (breast cancer) and H1299 (lung cancer)." (PMID 23826359, 2013).
breast cancer (continued). "To test whether a similiar scenario could be observed in migration/invasion-active primary breast cancer cells versus non-motile normal breast epithelial cells, we measured MMP-2 expression in the various HBCEC and in HMEC." (PMID 23457587, 2013). "Furthermore, MMP-1 and MMP-2 have been described as genes that selectively mediate lung metastasis in the MDA-MB-231 xenograft model of breast cancer and are members of a lung metastasis gene signature for human breast cancers." (PMID 19243594, 2009). "However, clinical studies on breast cancer are rare, limited in size and do not address the potential interaction of all three factors (MMP-2, MMP-14 and TIMP-2)." (PMID 16776850, 2006). "However, the association of ERBB2 expression with the expression of MMP-2 and MMP-9 has not previously been reported in breast cancer." (PMID 15054465, 2004). "Negative staining (MMP-2) was found in 22% of the primary tumours of breast carcinoma." (PMID 14520459, 2003). "It is possible that the lack of MMP-2 could become an important factor in certain subgroups of breast carcinoma when selecting the adjuvant therapy." (PMID 14520459, 2003). "The present data shows for the first time that MMP-2 negativity could serve as a marker for favourable prognosis in breast carcinoma patients with a hormone receptor-negative tumour usually associated with high risk." (PMID 14520459, 2003). "In addition to MMP-2 and MMP-9, MMP-1 has also been used as an accurate marker in a three markers scores model, including MMP-1, hepatocyte growth factor, and chemokine ligand 5, to predict axillary lymph node metastasis (LNM) positivity in breast cancer patients." (PMID 37181043, 2023). "Interestingly, GM3 is also able to induce MMP-2-mediated invasion of melanoma, and positively correlates with Ki-67 status in breast cancer, which is puzzling when considering that GM3 synthase silencing has been shown to decrease breast cancer metastases in vivo via NFAT1 inhibition." (PMID 35565181, 2022). "Therefore, exercise, in general, may not be an effective non-pharmacologic strategy to target MMP-2 in breast cancer patients undergoing anthracycline-based chemotherapy." (PMID 32246106, 2020). "In addition, the expression level of E-cadherin was up-regulated and expressions of Vimentin, MMP-2, MMP-9, Slug and Snail were reduced in the xenografts in the KIF3B-shRNA group compared with the control group by IHC staining, which were consistent with the results in breast cancer cell lines." (PMID 33542902, 2020). "However, we did not detect the changes of MMP2 protein in the breast cancer cell." (PMID 31346317, 2019). "Additionally, miR-206 was identified as tumor suppressor in breast cancer cell lines and was found to mediate this effect by directly targeting cell division cycle 42 (CDC42), resulting in down regulation of its protein expression together with that of MMP-2 and MMP-9." (PMID 24670365, 2014). "As the MDA-MB-231 breast cancer cells express all the four subtypes of PGE2 receptors, it remains to be determined whether the biphasic effect of PGE2 on their invasiveness and release of MMP-2 could be related to activation of different subtypes of its receptor." (PMID 21792195, 2011). "In a study with the breast cancer cell line MCF-7, metformin displayed inhibiting effects on MMP9 expression at 5.0 and 10.0 mmol/L after 24 h, whereas MMP2 levels were not affected." (PMID 37313172, 2023). "Analyzed by quantitative real-time PCR, nicardipine decreased MMP-9 mRNA expression in a dose-dependent manner; however, MMP-2 expression was not affected by nicardipine in 4T1, JC, and MDA-MB-231 breast cancer cells." (PMID 34483918, 2021). "This retrospective cohort study shows the immunohistochemical expression levels of MMP-1, MMP-2, MMP-3, and MMP-9 in 154 women with breast cancer and 42 women without tumor disease." (PMID 34445715, 2021).
breast cancer (continued). "Last but not least, miR-206 downregulates MMP2 and MMP9 leading to suppressed migration and invasion in MDA-MB-231 breast cancer cells." (PMID 33809973, 2021). "BAALC overexpression led to an increase in the expression of active MMP-9, but not active MMP-2, compared to EV expressing MCF-7 breast cancer cells." (PMID 33968759, 2021). "The combination of metronomic ZA and coriolus versicolor inhibits the growth breast cancer without increasing lung and liver metastasis through suppressing the expression of CD34 and MMP-2." (PMID 33143662, 2020). "Our results showed that ENO1, MMP-2 and MMP-9 are overexpressed in breast cancer tissues compared to the non-tumoral adjacent one, and how their higher expression level is associated with a worse prognosis." (PMID 31416219, 2019). "As accumulating evidence suggests the prognostic role of MMP-9 in breast cancer, the TNBC cells highly expressed MMP-9, whereas MMP-2 up-regulation was not consistent in various TNBC cell lines." (PMID 30185799, 2018). "Report of transient expression of SNCG in human breast cancer cells MDA-MB-435 and a recent study of stable expression of SNCG in colon cancer cells LS 174T did not alter the secretion of MMP2 or MMP9 in the CM." (PMID 29903032, 2018). "Unlike hormone-responsive breast cancer cells (MCF-7 and T47D), TNBC cells (MDA-MB-231, HCC-1973, and Hs578T) expressed higher levels of both MMP-2 and MMP-9." (PMID 30185799, 2018). "Zymography assays with 48- and 96-hr conditioned media revealed that breast cancer cells alone secrete a 92kDa zymogen form of MMP9 (pro-MMP9), whereas fibroblasts do not produce MMP9 but secrete significant amounts of MMP2/gelatinase-A." (PMID 28423685, 2017). "We found that a TNF-α-induced enhancement of breast cancer cell migration was accompanied by an increased secretion of MMP9, but not MMP2, into the culture media." (PMID 27042827, 2016). "We observed that MMP-2 and MMP-9 activities, among other MMP activities, are increased in metastatic breast cancer cell lines, xenografts, and lungs as compared with non-metastatic lines." (PMID 28721370, 2015). "Our study presents several important findings: (i) Increased expression and activity of MMP-2 and MMP-9 among others in metastatic breast cancer cell lines, xenografts, and lungs as compared with non-metastatic lines." (PMID 28721370, 2015). "In this study we evaluated genetic variation in MMP1, MMP2, MMP3, and MMP9 using data from a large collaborative case-control study of breast cancer in Hispanic and non-Hispanic white women (NHW) from the United States and Mexico." (PMID 23696797, 2013). "Human breast cancer cell lines, MDA-MB-231 and the MCF-10 series (M1, M2, and M4) were treated with or without the 100-nM MMP2/9 Inhibitor II for 24 h prior to transplantation into the zebrafish embryo." (PMID 24196484, 2013). "Conversely, it has been shown in pancreatic cancer cells that QSOX1 favored the activities but not the secretion of MMP-2 and MMP-9; whereas, QSOX1, in our breast cancer cell models, decreases both the activity and secretion of these MMPs." (PMID 23098186, 2012). "MMP-2, MMP-14 and TIMP-2 expression has been evaluated by 35S mRNA in situ hybridization on paraffin material of 539 breast cancers without distant metastasis at diagnosis and with a median follow-up of 9.2 years." (PMID 16776850, 2006). "In conclusion, we show here in a relatively large breast carcinoma patient group that MMP-2 immunoreactive protein is an independent prognostic indicator that might prove valuable in certain subgroups, such as patients with a receptor-negative breast carcinoma." (PMID 14520459, 2003). "Furthermore, MG-BSA-AGEs increase the expression of RAGE and ERK1/2 phosphorylation in different breast cancer cell lines, alongside increased expression of ER-α and ER-β without active forms of MMP-9/MMP-2 in ER positive cell lines." (PMID 39830522, 2024).